RDH5 (retinol dehydrogenase 5)
Description:
Catalyzes the oxidation of cis-isomers of retinol, including 11-cis-, 9-cis-, and 13-cis-retinol in an NAD-dependent manner. Has no activity towards all-trans retinal (By similarity). Plays a significant role in 11-cis retinol oxidation in the retinal pigment epithelium cells (RPE). Also recognizes steroids (androsterone, androstanediol) as its substrates.
Synonyms: 9cRDH; HSD17B9; RDH1; SDR9C5
Tractability: Antibody: UniProt predicts a signal peptide or a membrane-spanning region. PROTAC: its protein half-life has been measured.
Gene: Protein-coding gene on chromosome 12 (55,720,367 to 55,724,710, forward strand). Ensembl gene ENSG00000135437.
Subcellular location: Endoplasmic reticulum membrane
Subcellular location (Human Protein Atlas): Vesicles
Pathways (Reactome):
Disease: Defective visual phototransduction due to RDH5 loss of function
Sensory Perception: The canonical retinoid cycle in rods (twilight vision)
Signal Transduction: RA biosynthesis pathway
Gene Ontology:
Molecular function: all-trans-retinol dehydrogenase (NAD+) activity; androstan-3-alpha,17-beta-diol dehydrogenase (NAD+) activity; androsterone dehydrogenase [NAD(P)+] activity; protein homodimerization activity; 11-cis-retinol dehydrogenase (NAD+) activity; alcohol dehydrogenase (NAD+) activity; oxidoreductase activity, acting on the CH-OH group of donors, NAD or NADP as acceptor
Biological process: retinoid metabolic process; steroid metabolic process; visual perception; retinol metabolic process
Cellular component: endoplasmic reticulum lumen; endoplasmic reticulum membrane; cell body
Genetic constraint (gnomAD): Loss-of-function variants: 31 observed, 32.17 expected, observed/expected ratio (o/e) 0.96, 90% interval 0.72 to 1.3. The upper end of that interval is the gene's LOEUF score, 1.3, which puts it in group 5 of 6, group 1 being the genes least tolerant of losing a copy. Missense variants: 369 observed, 427.66 expected, observed/expected ratio (o/e) 0.86, 90% interval 0.79 to 0.94. Synonymous variants: 170 observed, 183.78 expected, observed/expected ratio (o/e) 0.93, 90% interval 0.82 to 1.05.
Gene-disease validity (ClinGen):
ClinGen rates the evidence that RDH5 causes each of these diseases.
RDH5-related retinopathy (autosomal recessive): Definitive. A retinopathy caused by bialleleic variants in the RDH5 gene, often involving flecks in the retina.
Homologues: Orthologues: chimpanzee RDH5 (99% identical), macaque RDH5 (98% identical), dog RDH5 (91% identical), rabbit RDH5 (89% identical), rat Rdh5 (87% identical), mouse Rdh5 (87% identical), pig RDH5 (86% identical), guinea pig RDH5 (85% identical), tropical clawed frog rdh5 (58% identical), zebrafish rdh5 (53% identical). Paralogues in human: RDH16 (52% identical), HSD17B6 (50% identical), SDR9C7 (47% identical), DHRS9 (44% identical), BDH1 (33% identical), HSD11B2 (31% identical), HSD17B2 (31% identical), HSD17B1 (26% identical), RDH11 (24% identical), SDR16C5 (24% identical), RDH10 (23% identical), RDH12 (22% identical), and 13 more.